FLOT2 (flotillin 2)
Diseases named in the same sentence as FLOT2 in open-access papers (continued):
Sharing a sentence is not in itself a finding about the gene and the disease.
tumor (29 papers, 2011 to 2025). "We found that Flot2-deficient mice exhibited delayed tumor growth and heightened resistance to Listeria infection, associated with augmented effector T cell proliferation and cytokine production." (PMID 39499901, 2024). "T cell–specific Flot2-deficient mice exhibited reduced tumor growth and enhanced immunity to infection." (PMID 39499901, 2024). "After confirming that Flot2 deficiency enhances effector T cell responses in vivo in both tumor and infection models, we investigated this phenomenon mechanistically, using reductionist in vitro approaches." (PMID 39499901, 2024). "Flotillin 2 (FLOT2) is a caveolae-associated protein that is involved in vesicular trafficking and tumor progression." (PMID 38730433, 2024). "In this study, we investigated Flot-2 expression in NPC cell lines and NPC tumor tissues and further explored the roles of Flot-2 in the development of NPC and the underlying mechanisms." (PMID 26206082, 2015). "Flotillin-2 (FLOT2) has been implicated in several signaling pathways in tumor cells." (PMID 23945257, 2013). "FLOT2 has been implicated in several signaling pathways in tumor cells." (PMID 23945257, 2013). "Our findings reveal that Flot2 deficiency enhances T cell responsiveness to low TCR stimulation, resulting in improved effector responses and tumor control in an in vivo tumor model, while mitigating T cell functional exhaustion." (PMID 39499901, 2024). "In both the B16F10 and MC38 models, Flot2–/– mice exhibited delayed/reduced tumor growth compared with Flot2+/+ counterparts." (PMID 39499901, 2024). "Overall, these data demonstrate that specific Flot2 deficiency in T cells boosts antitumor responses of both CD4+ and CD8+ T cells in murine tumor models." (PMID 39499901, 2024). "As a membrane protein, Flot2 promotes multiple tumor progression processes through different pathways such as Raf/MEK/ERK1/218, NF-κB, PI3K/AKT 21, and TGF-β 16, 29 pathways." (PMID 35173544, 2022). "Overall, these results suggest that miR-34a-5p can function as a tumor suppressor miRNA in HNSCC owing to its ability to target FLOT-2, highlighting the promise of targeting this regulatory axis to treat HNSCC." (PMID 34803501, 2021). "Next, we determined the levels of circ-FOXM1, miR-143-3p, FLOT2 mRNA, and FLOT2 protein in the collected tumor samples." (PMID 32183822, 2020). "Knocking down flotillin-1 or flotillin-2 in HCCLM3 cells by shRNA significantly lowered insufficient RFA-induced tumor growth, EMT changes, and metastasis in vitro and in vivo." (PMID 30820716, 2019). "In this study, we investigated FLOT1 and FLOT2 expression in insufficient RFA tumor tissues in vivo and in heat-treated HCC cells in vitro, and further explored the roles of flotillins in altering the metastatic potential of residual HCC cells." (PMID 30820716, 2019). "Elevated Flot2 in tumor tissue was an independent prognostic marker, and higher Flot2 expression level showed shorter overall survival time in 181 NPC patients." (PMID 25909165, 2015). "Protein expression of flotillin-2 was up-regulated in 53% of tumor samples compared to their normal tissue, and a high level of flotillin-2 was correlated with high and moderate differentiation degree (p < 0,05, χ2-test)." (PMID 24533441, 2014). "Notably, TCRα–/– recipients reconstituted with Flot2–/– bone marrow exhibited a significant reduction in tumor volumes compared with those reconstituted with WT bone marrow." (PMID 39499901, 2024). "Flot2 deletion enhances antitumor activity of T cells in murine tumor models." (PMID 39499901, 2024). "In addition, the increased expression of miR-485-5p altered the invasion of tumour cells by targeting the Flotillin-2 (FLOT2) protein, which led to a decrease in the ability of tumour cells to penetrate into surrounding tissues." (PMID 38203731, 2023).
tumor (continued). "In addition, Flot-2 reportedly plays a role in promoting tumor metastasis, such as and has been shown to induce metastasis in nasopharyngeal carcinoma by activating the NF-κB and PI3K/Akt3 signaling pathways." (PMID 35747825, 2022). "We, therefore, speculate that GC cells require not only increased Wnt3 expression levels for tumour maintenance but that increased Flot2 expression allows more effective ligand dissemination in the tumour tissue." (PMID 36040316, 2022). "A high level of expression of Flot-1 or Flot-2 can enhance tumor growth and tumor cell migration." (PMID 26206082, 2015). "Our previous study revealed that NPC tumor cells with high Flot-2 expression have a high metastatic potential, indicating that Flot-2 may be involved in NPC metastasis." (PMID 26206082, 2015). "Moreover, we analyzed the prognostic value of FLOT2 expression in selective patient subgroups stratified according to tumor grade and T classification (pT), respectively." (PMID 23945257, 2013). "Of interest, the more robust enhancement of antitumor immunity in the global Flot2-null mouse as compared with mice with T cell–specific Flot2 deletion also raises the possibility that Flot2 deletion in non–T cells (e.g., DCs, fibroblasts, endothelial cells) may contribute to tumor suppression." (PMID 39499901, 2024). "Furthermore, flotillin-1 also plays an important role in insulin signaling and cell proliferation, while flotillin-2 may influence tumor progression." (PMID 22023811, 2011). "Thus, flotillin-2 may play an important role in affecting tumor progression through interacting with PAR-1." (PMID 22023811, 2011). "It is concluded that miR-485-5p, as a tumor suppressor, inhibits the growth and metastasis in SCLC by targeting FLOT2." (PMID 30836864, 2019). "In conclusion, this study demonstrated that Flot-2 exerts a cancerous role in NPC and is involved in tumor progression and metastasis." (PMID 26206082, 2015). "Our results demonstrated that miR-485-5p acted as a tumor suppressor by directly targeting FLOT2, not FLOT1." (PMID 30836864, 2019). "Thus, Flot-2 exerts a pro-neoplastic role in NPC and is involved in tumor progression and metastasis." (PMID 26206082, 2015).
infection (7 papers, 2014 to 2024). The state of being infected such as from the introduction of a foreign agent such as serum, vaccine, antigenic substance or organism. "Following infection, Flot2–/– mice showed elevated resistance to weight loss compared with Flot2+/+ mice." (PMID 39499901, 2024). "To clarify the roles of the homologous flotillin 2 proteins in the infection of the two planthopper species by RRSV or SRBSDV, we tested the interactions between SFflotillin 2 and P10 of SRBSDV and those between NLflotillin 2 and P8 of RRSV." (PMID 35254088, 2022). "In this study, we demonstrated that flotillin 2 plays an important role in the infection of RSV and SRBSDV in their insect vectors." (PMID 35254088, 2022). "Here, we identified flotillin 2 as a plasma membrane protein that facilitates the infection of rice stripe virus (RSV) in its vector, the small brown planthopper." (PMID 35254088, 2022). "A. phagocytophilum captures cholesterol exclusively from LDL, and NPC1 and FLOT2 both target A. phagocytophilum inclusions and are required for infection." (PMID 34544283, 2021). "The cholesterol-sequestering agent MβCD abrogated FLOT2 localization to A. phagocytophilum inclusions and cleared infection." (PMID 34544283, 2021). "Furthermore, flotillin 2 mediated the infection of southern rice black-streaked dwarf virus in its vector, the white-backed planthopper." (PMID 35254088, 2022). "We identified flotillin 2 as a key factor on the plasma membrane of midgut epithelial cells which facilitates the infection of a persistent-circulative plant virus in its vector insect, and the specific interaction between flotillin 2 and the viral NP has a large effect on vector competence." (PMID 35254088, 2022). "Flotillin 2 may function as a key factor in the infection of several rice viruses in their vector insects." (PMID 35254088, 2022). "Strikingly, upon infection, a substantial proportion of FLOT2 was redistributed to non-LR fractions 8 and 9 that resulted in a dramatic increase in the proportion of non-LRs versus LRs." (PMID 34490251, 2021). "A loss-of-function mutant, NPC1P691S (mutation in the sterol-sensing domain), did not colocalize or interact with FLOT2 or with Anaplasma inclusions and inhibited infection." (PMID 34544283, 2021). "Therefore, flotillin 2 only mediates the infection of SRBSDV in the white-backed planthopper and not that of RRSV in the brown planthopper." (PMID 35254088, 2022). "Because NPC1 and FLOT2 are required for A. phagocytophilum infection and we found that ezetimibe blocks NPC1-FLOT2 colocalization and interaction, we examined whether ezetimibe could block infection of cells with A. phagocytophilum." (PMID 34544283, 2021). "Also depletion of other proteins involved in caveolae-mediated endocytosis, including caveolin 1 (CAV1) and flotillins 1 and 2 (FLOT1 and FLOT2) did not affect MHV infection or fusion." (PMID 25375324, 2014).
bacterial infections (1 paper, 2019). "FLOT1 is involved in several other intracellular bacterial infections, as FLOT1, but not FLOT2, localizes to C. pneumoniae inclusion membranes, and FLOT1 is important for C. pneumoniae intracellular growth, as determined by FLOT1 siRNA knockdown." (PMID 30914515, 2019).
FLOT2 also shares sentences with these, for which no sentence is quoted: kidney diseases (2 papers); nephrotic syndrome (2); prostate carcinoma (2); Alzheimer disease (1); anemia (1); arrhythmogenic right ventricular cardiomyopathy (1); asthma (1); chronic myeloid leukemia (1); colon adenocarcinoma (1); colorectal cancer (1); endometrial cancer (1); epilepsy (1); focal segmental glomerulosclerosis (1); gastric tumors (1); head and neck cancer (1); IgA nephropathy (1); intestinal tumour (1); leukemia (1); lung (1); membranous nephropathy (1); metastatic melanoma (1); minimal change disease (1); neurologic disease (1); Obesity (1); oral squamous cell carcinomas (1); osteosarcoma (1); small cell lung carcinoma (1); soft tissue sarcoma (1); thyroid cancer (1); viral infection (1).